TKT (transketolase)
Diseases named in the same sentence as TKT in open-access papers (continued):
Sharing a sentence is not in itself a finding about the gene and the disease.
cancer (continued). "NRF2 plays a crucial role in promoting the proliferation of cancer cells and metabolism process in lung cancer cells, including the direct transcriptional regulation of PPP-related enzymes such as G6PD, PGD, TKT, and TALDO1, which are responsible for NADPH regeneration." (PMID 33922165, 2021). "Transketolase (TKT) was found to regulate STAT3-Y705 and STAT3-S727 phosphorylation in cancers." (PMID 34376200, 2021). "Therefore, G6PD, 6PGD, and TKT are promising targets in the PPP for prevention and treatment of metabolic diseases and cancer." (PMID 32582032, 2020). "In the present study, we verified that TKT enzymatic activity could significantly increase the level of NADPH, which is the main reductant of cancer cells." (PMID 30971297, 2019). "Although the importance of TKTL1 in cancer proliferation, survival, and metabolism is well established, several reports have suggested that TKTL1 is incapable of enzymatically functioning as a TKT." (PMID 24280319, 2013). "In fact, the vast majority of ribose for nucleic acid biosynthesis in cancer cells is provided by the non-oxidative part of the PPP through activity of TKT and TAL." (PMID 23118983, 2012). "The identification of TKTL1, which participates in glucose metabolism in cancer cells, sheds a new light on this pathway, as TKTL1 represents an enzyme with transketolase activity and a potentially elevated substrate spectrum with altered reaction characteristics." (PMID 19812737, 2008). "As inhibition of transketolase enzyme reactions suppresses tumour growth and metastasis, TKTL1 could be the relevant target for novel anti-transketolase cancer therapies." (PMID 16465194, 2006). "It not only activates nucleic acid ribose synthesis through the non-oxidative transketolase-catalyzed pentose cycle reaction in cancer cells but also contributes to the proliferation of cancer cells by increasing energy production in the tumor cell environment." (PMID 38672799, 2024). "We found that suppression or knock-down of TKT markedly inhibited cell and tumor growth, regardless of the accumulation of ribose intermediates, indicating that ribose is not a restrictive factor in cancer growth." (PMID 39080260, 2024). "In addition, TKT can regulate cell cycle and promote the viability and proliferation of cancer cells independent of its enzyme activity." (PMID 32582032, 2020). "Furthermore, the increased protein expression in hyperplastic lesions and in both benign and malignant tumors compared to normal mammary gland suggests a significant involvement of the PPP and, consequently a role of TKT during the canine mammary carcinogenesis process." (PMID 28143530, 2017). "Our results indicate that the metabolic defects introduced by siRNA silencing of metabolic enzymes TKT or AK2 may be compensated by alternative feedback metabolic mechanisms, suggesting that cancer cells may overcome single defective pathways through secondary metabolic network adaptations." (PMID 24666435, 2014). "How thiamine supplementation impacts carbon flux through the non-oxidative pathway and modulates TKT activity in cancer cells is unknown." (PMID 24280319, 2013). "As transketolase reaction plays a vital role of the pentose phosphate pathway, inhibition of transketolase will suppress the pentose phosphate pathway and interrupt the synthesis of these important coenzymes ATP, CoA, NAD(P)+, FAD, and genetic material, RNA and DNA in cancer cells." (PMID 23890079, 2013). "Thus, a specific decrease in the activity of 2 key enzymes G6PDH and TKT, may lead to suppression of PPP that provides precursors of nucleotides for cancer cell cycle progression." (PMID 21849056, 2011).
cancer (continued). "PPP suppression has been used in cancer therapy apart from glycolysis, and the enzymes symbolic for the non-oxidative or oxidative phase of PPP are transketolase (TKT) and glucose-6-phosphate dehydrogenase, respectively." (PMID 36158697, 2022). "Transketolase (TKT) is a crucial enzyme in the non-oxidative phase of the Pentose Phosphate Pathway (PPP), and is up-regulated in multiple cancer types." (PMID 35280908, 2022). "TKT and TKTL1 rather than TKTL2 are essential for promoting cell growth and reducing oxidative stress in cancer cells." (PMID 32582032, 2020). "Transketolase (TKT), which is a metabolic enzyme in the nonoxidative phase of the pentose phosphate pathway (PPP), plays an important role in providing cancer cells with raw materials for macromolecular biosynthesis." (PMID 31949131, 2020). "In rapidly proliferating cancer cells, the non-oxidative PPP can be accelerated to meet the increased needs of ribonucleotides through elevated expressions of TKT and TALDO." (PMID 29285300, 2017). "TKT, rather than TKTL1 and TKTL2, was upregulated in cancers compared to non‐malignant tissues." (PMID 36314067, 2022).
tumor (102 papers, 2006 to 2026). "The positive association with E2F and MYC targets further implies that TKT supports tumor proliferation and progression by regulating TFs involved in cell cycle progression and metabolic control." (PMID 40230848, 2025). "In the group with mutations of IDH1 genes, the content of transketolase is higher in the tissue of the peritumoral zone and tumor." (PMID 35625744, 2022). "The level of transketolase in the peritumoral zone of the tumor was significantly higher for the IDH1 mutation group (U-criterion of Mann–Whitney p = 0.05; Kolmogorov–Smirnov criterion p = 0.1)." (PMID 35625744, 2022). "In CRC, TKT expression was predicted to be enhanced during cell cycle progression, and up-regulation of TKT was associated with invasive tumor cells." (PMID 35280908, 2022). "We also observed that the 4 prognosis-associated genes RHOB, TALDO1, HLA-DPA1, and TKT were simultaneously elevated in the tumor and peripheral blood in patients with HCC." (PMID 35856557, 2022). "It follows that TKT has been found to influence the cellular redox balance, where its knockdown causes an accumulation of intracellular ROS, sensitising tumour cells to radio- and chemotherapies." (PMID 33627789, 2021). "We also found that the Y4A and K6R mutations decreased the tumor-promoting effects of TKT, even in the presence of a dominant-negative mutation of the enzyme activity." (PMID 30971297, 2019). "On the other hand, the role of TKT in tumor-cell metabolism has been underlined by reports of a significant decrease in tumor-cell proliferation following treatment with specific TKT inhibitors, both in vitro and in vivo." (PMID 21980427, 2011). "In addition, the expression of TKT is increased in tumor cells, and overexpression of TKT is associated with tumor invasion and poor prognosis." (PMID 40227333, 2025). "Furthermore, 4 common prognosis-associated genes (RHOB, TALDO1, HLA-DPA1, and TKT) were significantly overexpressed in the paired tumor tissue and blood." (PMID 35856557, 2022). "KPNA2 and TKT were broadly and highly expressed within tumor regions, suggesting their potential involvement in tumor proliferation or metabolic activity." (PMID 41602397, 2026). "In general, TKT inhibition enhances the tumor-suppressive effect of cisplatin by modulating the levels of R5P, NADPH, and ROS, further promoting cisplatin-induced DNA damage." (PMID 40227333, 2025). "In HCC, TKT expression positively correlates with tumor stemness, which promotes tumor initiation, metastasis, and drug resistance." (PMID 40230848, 2025). "In such tumors, high expression of TKT helps tumor cells to better cope with metabolic stress and oxidative damage, which in turn increases their drug resistance and enhances metastasis." (PMID 40230848, 2025). "Owing to its distinct metabolic influence, the inhibition of TKT holds the potential to foster tumor cell apoptosis through the elevation of ROS levels." (PMID 40227333, 2025). "This pattern highlights the potential role of TKT in the interaction between malignant and immune cells, facilitating tumor progression." (PMID 40230848, 2025). "The involvement of TKT in oncogenic pathways and its effects on the tumor microenvironment highlight its potential as a therapeutic target." (PMID 40230848, 2025). "This metabolic shift contributes to TKT-mediated tumor progression, particularly under the nutrient- and oxygen-deprived conditions of the RCC microenvironment." (PMID 41253799, 2025). "Analysis of TKT expression in the 53 CH-CMU-obtained NB tumor tissues indicated TKT enrichment in BBM." (PMID 40070366, 2025). "In these tumors, TKT expression reduces oxidative damage, thereby protecting tumor cells from the adverse impacts of metabolic imbalance." (PMID 40230848, 2025). "Pharmacological inhibition of PPP, specifically targeting transketolase (TKT) with oxythiamine, reprograms macrophages toward a pro-inflammatory, anti-tumor phenotype." (PMID 40076729, 2025).
tumor (continued). "Immunohistochemical (IHC) analysis confirmed that TKT was significantly overexpressed in tumor tissues." (PMID 41253799, 2025). "The results showed that TKT knockdown significantly reduced the tumor volume and weight compared with the control." (PMID 40070366, 2025). "While transketolase (TKT), a central metabolic enzyme, has been shown to exert dichotomous roles as either oncogenic or tumor-suppressive factors across different malignancies, its functional significance in RCC pathogenesis remains inadequately defined." (PMID 41253799, 2025). "The results showed that the expression of TKT in tumor tissues of patients with poor response to immunotherapy was significantly higher than that of patients with a good response." (PMID 40230848, 2025). "In the CPTAC-LIHC cohort, TKT protein levels were significantly elevated in tumor tissues compared to normal tissues, suggesting a potential role in the pathogenesis of LIHC." (PMID 40230848, 2025). "Conversely, in the TKT overexpression group, tumor size and weight were significantly increased compared to the vector control group, and the tumor growth rate was markedly accelerated." (PMID 41253799, 2025). "TKT, the major type of transketolase, is expressed in normal human organs and most tumor tissues, while TKTL1 and TKTL2 are mainly expressed in the testis." (PMID 40227333, 2025). "Clinical data showed that the expression level of TKT in tumor tissues was higher than that in adjacent tissues, and the expression level of TKT was negatively correlated with overall survival." (PMID 40227333, 2025). "First, WB results showed that the expression of TKT in A549/DDP and H460/DDP was higher than that in A549 and H460, indicating that TKT was over-activated during the formation of tumor chemotherapy resistance." (PMID 40227333, 2025). "TKT expression was positively associated with the EMT pathway, which is crucial for tumor metastasis and invasion." (PMID 40230848, 2025). "We evaluated the association of expression of TKT in HCC tissues with prognosis, and investigated the inhibitory effect of lycorine on tumor growth in vivo." (PMID 38434975, 2024). "In order to study the effect of TKT inhibition on HMGA1-induced tumor progression, we applied TKT inhibitor OT or PBS into mice by gavage every day." (PMID 39080260, 2024). "The expression of TKT was significantly correlated with tumor size and Edmondson grade, and AFP (P<0.01)." (PMID 38434975, 2024). "The expression of TKT showed a significant increase in tandem with the progression of HCC tumor grade, and high TKT expression was indicative of a poor prognosis for HCC, as per TCGA dataset." (PMID 38216672, 2024). "This is the first time that the expression of TKT has been correlated with tumor staging and metastasis in LUAD." (PMID 35711845, 2022). "Previous reports have indicated that an inhibitor of TKT, oxythiamine, decreased cell proliferation through inhibition of the pentose cycle and induced a G1 phase arrest in tumour cells." (PMID 35752610, 2022). "The obvious positive correlation with the high expression of TKT were tumor lymph node metastasis (P < 0.001) and tumor node metastasis (TNM) stage (P < 0.001)." (PMID 35110545, 2022). "The expression of TKT in tumor tissues of patients with CRC is significantly higher than adjacent tissues." (PMID 35110545, 2022). "The expression of TKT was strongly positive in the tumor tissues, and the number of cells expressing TKT was significantly increased." (PMID 35711845, 2022). "The data demonstrated that compared with adjacent normal tissues, TKT expression was significantly upregulated in tumor tissues, and increased TKT expression was also detected in the Gene Expression Profiling Interactive Analysis (GEPIA)." (PMID 35110545, 2022). "As an important member of the PPP, TKT has been found highly expressed and plays an important role in tumor development." (PMID 35110545, 2022).
tumor (continued). "Correspondingly, TKT depletion was detected in HepG2 xenograft tumours and DEN‐induced liver tumours, which was confirmed by immunohistochemical staining." (PMID 36314067, 2022). "With a high level of the mitotic index Ki-67, there is a lower activity of transketolase in the tissues of the tumor (significant) which indicates the decrease in the activity of the oxidative stage of the pentose phosphate pathway." (PMID 35625744, 2022). "TKT, which is expressed in all investigated organisms and most tumor tissues, enables cells to meet their anabolic demands under different conditions and to convert glucose to ribose for nucleic acid synthesis." (PMID 35280908, 2022). "High TKT expression was significantly correlated with characteristics of a poor prognosis, such as shorter overall survival (P = 0.009), metastasis of tumor (P = 0.038) and more serious clinical conditions (P = 0.03)." (PMID 35711845, 2022). "With a high mitotic index of Ki-67 in the tumor tissue, the level of glucose, transketolase, and glycogen synthase kinase 3β is reduced." (PMID 35625744, 2022). "The non-oxidative arm of PPP is also important for tumor cells, based on higher expression and activity of transketolase, which correlates with the rate of tumor growth in some cancers, including GBMs." (PMID 34277624, 2021). "Previous studies have focused on TKT as a metabolic enzyme regulating the PPP pathway to affect tumor cell proliferation." (PMID 31949131, 2020). "TKT was the majority of transketolase not only in human normal organs but also in most tumor tissues while TKTL1 and TKTL2 are mainly expressed in testis." (PMID 30971297, 2019). "The underexpression trend of TKT in the more aggressive neoplasm suggests that probably a further molecular pathway exists that limits or inhibits the protein expression in the most aggressive and life-threatening mammary neoplastic histotype." (PMID 28143530, 2017). "It participates in the regulation of the antioxidant defense, chemoresistance, tumorigenesis and tumor progression, in part by promoting anabolic reactions such as those catalyzed by TKT and G6PD." (PMID 29290982, 2017). "Oxythiamine is an analogue of the cofactor TPP and inhibits TKT activityin human tumour cells in vivo, although it is only a weak inhibitorin vitro." (PMID 22645655, 2012). "G6PDH and TKT, which control the pathway, are enough to explain the basic metabolic features acquired by tumor cells during their transformation." (PMID 21980427, 2011). "Coy indicated that tumor cells which upregulate transketolase enzyme reactions can use glucose as an energy source through nonoxidative generation of ATP." (PMID 19331662, 2009). "It has been presumed that transketolase activity possibly plays an important role in the tumor cell proliferation." (PMID 19331662, 2009). "Metabolic control analysis and inhibition of transketolase enzyme reactions have already shown that tumour proliferation can be inhibited by anti-transketolase approaches." (PMID 16465194, 2006). "Tumour cells that upregulate transketolase enzyme reactions can use glucose as an energy source through nonoxidative generation of ATP." (PMID 16465194, 2006). "Further dot plot analysis revealed that TKT and KPNA2 were relatively highly expressed in epithelial and myeloid cells, with TKT showing notably higher expression in tumor epithelial cells compared to normal epithelial cells, suggesting its potential involvement in tumorigenesis or progression." (PMID 41602397, 2026). "Specifically, that TKT may regulate the response of HCC to different drug therapies through metabolic reprogramming in tumor cells, thereby affecting its efficacy." (PMID 40230848, 2025).